INS (insulin)
Diseases named in the same sentence as INS in open-access papers (continued):
Sharing a sentence is not in itself a finding about the gene and the disease.
diabetes (continued). "Insulin-dependent diabetes mellitus was excluded by normal serum glucose, insulin, and C-peptide level, as well as absence of autoimmune antibodies associated with T1D (islet cell antibody, glutamic acid decarboxylase antibody, insluinoma-associated 2 molecule antibody and insulin autoantibody)." (PMID 32358377, 2020). "Furthermore, missing data including insulin dose and non-diabetes related causes of low magnesium concentrations such as decreased intake or malabsorption, or increased gastro-intestinal loss, for example, due to diarrhoea or medication, cannot be excluded in the present cohort." (PMID 33447354, 2020). "This impact may be identified for diabetes in two longitudinal studies in which low social support was the single component of the model associated to the risk of diabetes; in addition, low social support was also associated to a higher resistance to insulin." (PMID 32120955, 2020). "Reduced insulin secretion, insulin resistance, arteriosclerosis, chronic inflammation, oxidative stress, mitochondrial dysfunction, poor glycemic control, decreased physical activity, and malnutrition in diabetes are potential causes of frailty and cognitive impairment observed in these patients." (PMID 33139628, 2020). "On the other hand, leptin might be used as an adjunct to insulin therapy in patients with insulin-deficient diabetes, providing insight into its therapeutic properties as an antidiabetic agent; moreover, leptin monotherapy has been reported to reverse type 1 diabetes independent of insulin." (PMID 33167521, 2020). "Moreover, another study recruiting postmenopausal women suggested that diabetes increased the risk of lung cancer (hazard ratio: 1.27, 95% confidence interval: 1.02–1.59), which was more remarkable among patients treated with insulin (hazard ratio: 1.71, 95% confidence interval: 1.15–2.53)." (PMID 32498358, 2020). "This study seeks to determine whether daily administration of oral insulin, from the age of 4–7 months until the age of 36 months to children with elevated genetic risk for T1D, reduces the incidence of beta cell autoantibodies and diabetes." (PMID 32670194, 2020). "The risk factors for MCI in patients with type 2 diabetes mellitus may include hypertension, obesity, presence of dyslipidemia, effects of exogenous and endogenous insulin associated with the treatment of diabetes, degree of chronic hyperglycemia, duration of diabetes, and presence of hypoglycemia." (PMID 32640726, 2020). "Thus, it remains unclear whether insulin therapy worsens COVID-19 outcomes or if these results were caused by a patient selection bias (note: patients with diabetes receiving insulin tend to have longer duration of disease with a higher rate of comorbidities)." (PMID 33335527, 2020). "As a metabolic disorder, diabetes mellitus (DM) is caused either by a deficiency of insulin’s mechanism of action, by an insulin secretion deficit, or by both." (PMID 33007040, 2020). "Adipocyte fatty acid binding protein (A-FABP), an adipokine that has been implicated in lipid metabolism, lipolysis, and insulin sensitivity, can be used to predict the incidence of metabolic syndrome (MetS) and type 2 diabetes mellitus (DM)." (PMID 33080960, 2020). "Because improved insulin sensitivity secondary to weight loss is a significant contributor to the improvement and reversal of type 2 diabetes mellitus (T2DM), our findings suggest that PAI-1 might be involved in the pathophysiology of T2DM and insulin resistance." (PMID 32670063, 2020). "Diabetes mellitus (DM) is a group of metabolic diseases characterized by hyperglycemia and caused by insufficient insulin secretion and/or defective insulin action." (PMID 31942181, 2020). "Diabetes mellitus (DM), which is caused by defective insulin secretion or insulin sensitivity, has been a large public health burden." (PMID 31969494, 2020).
diabetes (continued). "These phytoconstituents protect cellular antioxidant defense mechanism from oxidative stress, stimulate insulin signaling pathway, and regulate transcription factors, hormones, peptides, and inflammatory pathways for the management of hyperglycemic condition and diabetes-associated complications." (PMID 32256963, 2020). "The WHO defines obesity as “abnormal or excessive fat accumulation that may impair health,” and diabetes as a “chronic disease caused by inherited and/or acquired deficiency in production of insulin by the pancreas, or by the ineffectiveness of the insulin produced”." (PMID 32423144, 2020). "While the Society of Critical Care Medicine and American Diabetes Association guidelines suggest achieving glucose < 180 mg/dL in critically ill patients on an insulin infusion, lower goals (<150 mg/dL) may be used if a low incidence of hypoglycemia is maintained." (PMID 33198177, 2020). "Diabetes mellitus (DM) is a metabolic disease associated with the inability to produce insulin and the inability to properly utilize glucose (T1D) or insulin resistance when interacting with its receptor (T2D)." (PMID 33035272, 2020). "However, the glucose-increasing alleles in the fetus are associated with reduced birth weight, which is in line with the epidemiological finding that paternal diabetes is associated with lower birth weight and with the fetal insulin hypothesis." (PMID 32841251, 2020). "It has been proven that insulin therapy through the regulation of metabolic mechanisms and immune responses may improve glycemic control and reduce the risk of long-term complications in persons with diabetes." (PMID 32626786, 2020). "Diabetes mellitus (DM) is a diverse metabolic disorder characterized by elevated blood sugar levels as a result of deficiency of insulin secretion, defective insulin action or both." (PMID 32903276, 2020). "In addition, glucose may program DBMSCs into insulin producing cells with ability to counteract inflammation and infection associated with diabetes." (PMID 32077075, 2020). "Finally, a recent study has shown that it could sometimes be used successfully to replace insulin in neonatal diabetes associated with chromosome 6 methylation abnormalities." (PMID 33102403, 2020). "Diabetes mellitus (DM) is a chronic metabolic disease characterized by either absolute and/or relative deficiency of insulin production or action or both." (PMID 32342229, 2020). "Diabetes mellitus (DM) is a serious chronic metabolic disease caused by a relative or absolute deficiency in insulin secretion." (PMID 32756447, 2020). "Furthermore, the increased risk of recurrent strokes and death in patients with diabetes may be the result of vascular changes caused by the synergistic effect of chronic hyperglycaemia, free fatty acids release and insulin resistance." (PMID 32489775, 2020). "In addition, we tested that whether use of oral anti-diabetic medications, insulin, aspirin, and statins affect prostate cancer risk among men with diabetes." (PMID 32467600, 2020). "Interestingly, decreased circulating insulin in diabetes is associated with increased FoxO1 activation, whereas mitochondrial reactive oxygen species (ROS) production was enhanced by altering redox balance and impacting the activity of redox‐sensitive proteins, such as protein kinase C‐ε." (PMID 33108705, 2020). "However, these compensatory mechanisms ultimately lead to high circulating levels of insulin, or hyperinsulinemia, which in a vicious cycle worsens the peripheral insulin resistance and contributes to the metabolic dysregulations associated with diabetes." (PMID 32150819, 2020). "Therefore, it is worthwhile to note that, due to the loss of insulin signaling from the compromised beta cells in diabetes mellitus, the development and functionality of the other endocrine cells could be affected." (PMID 31979403, 2020).
diabetes (continued). "The association of HGS with diabetes may be justified by its intimate connection with muscle mass, which plays an important role in the use of blood glucose, also due to its size and responsiveness to insulin." (PMID 32216788, 2020). "Diabetes mellitus (DM) is a type of metabolic disorder caused by insufficient insulin secretion or insulin utilization disorder, and is marked by persistent hyperglycemia." (PMID 32378043, 2020). "However, low grain intakes may be associated with recruitment from high risk Gestational Diabetes clinics as patients were all on insulin and seeing a Dietitian once a fortnight." (PMID 32823663, 2020). "T2D is the most prevalent form of diabetes mellitus, a chronic disease characterized by increased plasma glucose levels due to insulin secretion deficiencies (i.e., β-cell dysfunction) and IR (i.e., decreased target tissue capacity to react regularly to insulin)." (PMID 32063863, 2019). "Thus, impaired pancreatic β-cell responsiveness and decreases in circulating insulin caused by pancreatic acinar cell exposure to hyperglycemia, which results in oxidative stress, may play important roles in the susceptibility of diabetics to AP." (PMID 31624312, 2019). "The results therefore indicate that DF efficiently regulates blood glucose by conserving β-cell population and retaining insulin levels and thereby protects DM mice from diabetes-associated tissue damages." (PMID 30987324, 2019). "Diabetes mellitus (DM) is characterized by a bunch of chronic metabolic diseases leading to insulin-secretion deficiency." (PMID 30891058, 2019). "However, data from the German prospective cohort studies BABYDIAB and BABYDIET suggested that SLC30A8 may influence age at onset of diabetes and rate of progression within predisposed individuals, perhaps by its effect on insulin production." (PMID 31444530, 2019). "Therefore, deciphering the molecular mechanism underlying insulin-induced adipokine release could potentially lead to new therapeutic interventions against obesity and diabetes." (PMID 30754657, 2019). "Autoimmune Diabetes Mellitus (DM) is a chronic disease caused by the selective destruction of insulin producing beta cells in human pancreas." (PMID 30696851, 2019). "Interestingly, the increase in extracellular adenosine can result from the metabolic and hormonal breakdown present in diabetes, such as the deficient activity of insulin, and directly affect the uptake and extracellular metabolism of adenosine at the renal level." (PMID 31540220, 2019). "Diabetes mellitus (DM) describes a metabolic disorder characterized by a deficiency in insulin production and its action or both." (PMID 30723516, 2019). "Diabetes mellitus (DM) is one of the most common metabolic diseases which is associated with either impairment of insulin secretion (type I diabetes) or tolerance of cells to insulin (type II diabetes)." (PMID 31480399, 2019). "Maturity-onset diabetes of the young (MODY) is characterized by the occurrence of early-onset diabetes mellitus (DM), most often before age 25, with dominant autosomal inheritance caused by primary defects in insulin secretion." (PMID 31066763, 2019). "Diabetes mellitus (DM) is a metabolic disorder accompanied by hyperglycemia resulting from insulin production deficiency, insulin resistance, or both leading to a variety of complications." (PMID 31509596, 2019). "Diabetes mellitus (DM) is a clinical syndrome, characterized by hyperglycemia, caused by inherited and/or acquired deficiency in insulin production and/or action." (PMID 30897827, 2019). "The parameters associated with insulin requirement in total population were as follows; maternal age ≥ 35 years, family history of diabetes mellitus (DM), pre-pregnancy BMI, previous history of spontaneous abortion, and prior history of GDM." (PMID 31656196, 2019).
diabetes (continued). "RES-treated Caucasian subjects who showed improvement in insulin sensitivity and glucose homeostasis also had a significant increase in A. muciniphila, a microbe that, in experimental animals, has been inversely associated with obesity, diabetes, and low-grade inflammation." (PMID 30873501, 2019). "Diabetes mellitus (DM) is a serious, chronic disease which occurs either when the body does not use the insulin produced by itself effectively meaning insulin resistance (type 2 DM) or when the pancreas cannot produce sufficient insulin meaning insulin deficiency (type 1 DM)." (PMID 31089416, 2019). "They suggest that proteins implicated in mitochondrial dysfunction decrease to a greater extent as diabetes progresses to insulin dependence, indicating that mitochondrial changes may be linked to diabetes insulin therapy itself or disease conditions at the time of transition to insulin therapy." (PMID 31275634, 2019). "Damages induced by ROS and/or the failure of antioxidant defenses, may cause several defects in insulin biogenesis and secretion in β cells, but also peripheral insulin-sensitive tissues dysfunction and damage, thus contributing to the onset of diabetes and its complications." (PMID 31861156, 2019). "Diabetes mellitus (DM) is a chronic syndrome of impaired carbohydrate, protein, and fat metabolism caused by insufficient secretion of insulin and/or defects in insulin action in tissues due to insulin resistance." (PMID 31108850, 2019). "Diabetes mellitus (DM) is a metabolic disorder characterized by the presence of high levels of glucose in blood that occurs either due to insulin's deficiency or malfunction." (PMID 31708869, 2019). "Whilst some evidence suggests that obesity may modulate the association between APOE genotype and fasting insulin and glucose levels, and hence potentially inflammation in men, other studies point to independent effects of obesity, diabetes, and APOE genotype to LOAD risk." (PMID 30735826, 2019). "One study addressing MRDM highlighted the low binding of insulin to blood cells,which reflects insulin resistance and that is consistent with longitudinal evidencewhich supports the correlation between low birth weight and cardiovascular risksincluding insulin resistance known to cause diabetes." (PMID 31673335, 2019). "Diabetes mellitus (DM) is a complex and chronic metabolic disease characterized by hyperglycemia due to deficiency of insulin secretion or insulin resistance." (PMID 30918104, 2019). "However, an insufficient dose of insulin easily induces extreme hyperglycemia or diabetic ketoacidosis, and intensive insulin therapy may cause hypoglycemic symptoms including hypoglycemic shock." (PMID 30781427, 2019). "As high copeptin has been repeatedly shown to be a strong independent risk factor for diabetes, the second aim of our study was to investigate if a reduction of copeptin by increased water intake for 1 week may influence glycemia, insulin or glucagon concentrations." (PMID 29242971, 2019). "Besides, repeated exposure to fluoride has been shown to increase serum glucose in animals with STZ-induced diabetes; which could be caused by reduced secretion of insulin in pancreatic beta cells." (PMID 31885555, 2019). "Hyperglycemia in diabetes provokes production of mitochondrial reactive oxygen species (ROS) and protein glycation, leading to an exaggerated ER load of misfolded/unfolded and nascent proteins associated with insulin production and release, which impairs ER homeostasis and causes ER stress." (PMID 31061237, 2019). "Therefore, the present study aimed at investigating whether human insulin use would affect lung cancer risk in Taiwanese patients with type 2 diabetes mellitus." (PMID 31354621, 2019).
diabetes (continued). "Interestingly, another study revealed that higher plasma ceramide content, along with saturated FA concentrations, are prospectively associated with higher fasting insulin and insulin resistance in the Strong Heart Family Study cohort (a population at high risk of diabetes)." (PMID 30678043, 2019). "Therefore, enhancing MC4R function may minimize the risk of life-threatening hypoglycemia caused by insulin or its secretagogues during the treatment of diabetes." (PMID 30503832, 2019). "Diabetes mellitus (DM) is a group of metabolic diseases characterized by hyperglycemia and caused by defects in insulin secretion, insulin function, or both." (PMID 31104419, 2019). "Hence, vitamin E in the form of tocotrienol-rich fraction (TRF) may also boost insulin sensitivity and decrease diabetes risk by quenching free radicals and simultaneously reducing oxidative stress in the body." (PMID 31635074, 2019). "Further, insulin is recognized to be an important growth factor and studies indicate that there could be genetic alleles that might both reduce fetal growth and cause an impaired insulin secretion and hence, predispose to diabetes." (PMID 30430243, 2019). "In the course of diabetes development, a variety of miRNAs carried by exosomes, including miR-155 and miR-204, can facilitate the occurrence of diabetes by causing insulin resistance, reducing the sensitivity of the body to insulin, and activating mitochondrial apoptosis in β cells." (PMID 31736691, 2019). "Thus, attenuation or restoration of Lepr in adipocytes alters the plasma insulin profile following glucose ingestion, modifies the glucose-lowering effect of prolonged leptin therapy in insulin-deficient diabetes, and may modulate weight gain." (PMID 30824713, 2019). "The adipokine adiponectin could induce insulin-sensitizing effects and its elevated level has been associated with improved insulin sensitivity and glucose tolerance and could protect women against the development of diabetes after menopause." (PMID 30863274, 2019). "From a health policy perspective, two forms of diabetes in particular play an important role: immune-mediated type 1 diabetes, which generally leads to absolute insulin deficiency, and type 2 diabetes, in which both insulin resistance as well as reduced insulin secretion play a role." (PMID 35146246, 2019). "Moreover, long-term insulin therapy may also be responsible for increased risk of endometrial cancer in women with diabetes." (PMID 31151429, 2019). "The benefits of assessing the glycemic index of foodstuffs serve as glucose control, control of insulin demands, and low concentration of lipids in the blood, which are invariably linked to the control and/or prevention of diseases such as cardiovascular disease, diabetes, and hypertension." (PMID 30680164, 2019). "Impaired renal function affects the efficacy of elimination of oral glucose lowering drugs (particularly an issue for sulfonylurea) and insulin, whereas dementia may adversely affect patients’ ability to self-manage their diabetes, and both are associated with increased risk of serious hypoglycemia." (PMID 31477024, 2019). "Furthermore, CFAH presence has also been linked with decreased insulin production from rat pancreatic cells and it may play a role in the pathogenesis of diabetes." (PMID 30922315, 2019). "The p.Gly32Ser pathogenic variant in the INS gene (patient 11) is known to cause proinsulin misfolding and has been previously reported in patients with permanent neonatal diabetes and also in patients with diabetes onset during infancy, childhood or adulthood." (PMID 31365591, 2019). "Type 2 Diabetes is the most common form of DM known by the body’s progressive resistance to the normal actions of insulin and/or gradual loss of the capacity to produce enough insulin in the pancreas." (PMID 31048925, 2019).